TAPBPL (TAP binding protein like)
Description:
Component of the antigen processing and presentation pathway, which binds to MHC class I coupled with beta2-microglobulin/B2M. Association between TAPBPR and MHC class I occurs in the absence of a functional peptide-loading complex (PLC).
Synonyms: TAPBP-R; FLJ10143; TAPBPR
Tractability: Small molecule: a structure with a bound ligand is known. Antibody: UniProt places it where antibodies can reach, with high confidence; UniProt predicts a signal peptide or a membrane-spanning region; its Gene Ontology location is reachable by antibodies, with medium confidence. PROTAC: ubiquitination databases record sites on it; its protein half-life has been measured.
Gene: Protein-coding gene on chromosome 12 (6,451,690 to 6,466,517, forward strand). Ensembl gene ENSG00000139192.
Subcellular location: Cell membrane; Endoplasmic reticulum membrane; Microsome membrane; Golgi apparatus membrane
Gene Ontology:
Molecular function: MHC class I protein complex binding; protein binding; TAP complex binding
Biological process: negative regulation of antigen processing and presentation of peptide antigen via MHC class I; peptide antigen assembly with MHC class I protein complex
Cellular component: endoplasmic reticulum; Golgi membrane; MHC class I peptide loading complex; endoplasmic reticulum membrane; plasma membrane
Genetic constraint (gnomAD): Loss-of-function variants: 32 observed, 43.2 expected, observed/expected ratio (o/e) 0.74, 90% interval 0.56 to 1. The upper end of that interval is the gene's LOEUF score, 1, which puts it in group 4 of 6, group 1 being the genes least tolerant of losing a copy. Missense variants: 520 observed, 595.28 expected, observed/expected ratio (o/e) 0.87, 90% interval 0.81 to 0.94. Synonymous variants: 230 observed, 245.44 expected, observed/expected ratio (o/e) 0.94, 90% interval 0.84 to 1.04.
Homologues: Orthologues: chimpanzee TAPBPL (99% identical), macaque TAPBPL (83% identical), rabbit TAPBPL (68% identical), pig TAPBPL (68% identical), dog TAPBPL (65% identical), mouse Tapbpl (65% identical), guinea pig TAPBPL (62% identical), rat Tapbpl (62% identical), zebrafish tapbpl (29% identical), tropical clawed frog tapbpl (27% identical). Paralogues in human: TAPBP (25% identical), NCR3LG1 (13% identical).
Diseases named in the same sentence as TAPBPL in open-access papers:
TAPBPL is named in the same sentence as 18 diseases in open-access papers, as found by Europe PMC text mining. Sharing a sentence is not in itself a finding about the gene and the disease. The quoted sentences say what the papers report.
breast carcinoma (2 papers, 2014 to 2020). "All eight cis-eQTL/TAPBPL associations are represented in Breast Cancer." (PMID 25133526, 2014). "The cis-eQTL associations of 7 genes (TAPBPL, H1F0, SERPINB9, HMBOX1, MGST3, TMBIM4, THNSL2) are shared between GBM and cell lines/normal tissues; the association of 4 genes (TAPBPL, H1F0, HMBOX1, THNSL2) are common between GBM and Breast Cancer." (PMID 25133526, 2014). "Like ERRα activity, the mRNA levels of ERRα target genes, KLK3, ENO1 or TAPBPL, were also significantly elevated in GREM1-overexpressing breast cancer cells." (PMID 32572171, 2020).
melanoma (2 papers, 2021 to 2022). A malignant, usually aggressive tumor composed of atypical, neoplastic melanocytes. "Furthermore, we analyzed the expression of TAPBPL on cancer cells following IFNγ stimulation in vitro and found that the expression levels of TAPBPL on neuro‐2a neuroblastoma and B16F10 melanoma were upregulated upon stimulation (Fig EV1G and H)." (PMID 33938620, 2021). "TAPBPL was expressed highly on the cell surface of murine neuro‐2a neuroblastoma and P388 leukemia cells, and weakly on murine Lewis lung carcinoma, CT‐26 colon cancer, and B16F10 melanoma cells." (PMID 33938620, 2021).
Arthritis (1 paper, 2023). Inflammation of a joint. "As a model for human RA, we investigated the ability of the TAPBPL protein to ameliorate collagen type II (CII)-induced arthritis (CIA) in mice that were injected with recombinant TAPBPL or a control protein." (PMID 37762076, 2023).
autoimmune disease (1 paper, 2021). A disorder resulting from loss of function or tissue destruction of an organ or multiple organs, arising from humoral or cellular immune responses of the individual to their own tissue constituents. "Targeting the TAPBPL pathway may represent a new strategy to modulate T cell‐mediated immunity to treat autoimmune disease and cancer." (PMID 33938620, 2021). "Our results suggest that therapeutic intervention of the TAPBPL inhibitory pathway may represent a new strategy to modulate T cell‐mediated immunity for the treatment of cancer, infections, autoimmune diseases, and transplant rejection." (PMID 33938620, 2021). "Therefore, targeting the TAPBPL has the potential to be used in the treatment of autoimmune diseases (such as MS) and transplant rejection, as well as cancer and infection." (PMID 33938620, 2021). "A soluble TAPBPL‐Ig fusion protein inhibits the proliferation and activation of CD4 and CD8 T cells in vitro and ameliorates autoimmune disease EAE in vivo." (PMID 33938620, 2021).
cervical cancer (1 paper, 2020). A primary or metastatic malignant neoplasm involving the cervix. "Four of these genes were also significantly up-regulated in cervical cancer cell lines (SiHa and C33A):EIF3K (p = 0.0092), RACK1 (p = 0.0086), TAPBPL (p = 0.0011) and BTNL8 (p = 0.0012)." (PMID 32025240, 2020).
Infertility (1 paper, 2021). "Other major DEPs, including RNASEH2C, TAPBPL, TUBB8, NFRKB, MASTL, and MYLK, have never been reported to be associated with infertility, metabolic disorders, or hormone imbalances." (PMID 34016141, 2021).
leukemia (1 paper, 2021). A malignant (clonal) hematologic disorder, involving hematopoietic stem cells and characterized by the presence of primitive or atypical myeloid or lymphoid cells in the bone marrow and the blood. "TAPBPL protein is also expressed on the surface of T cells, and antigen‐presenting cells (APCs) including resting B cells, monocytes, macrophages, and DCs, as well as on some cancer cells including leukemia cells." (PMID 33938620, 2021).
prostate carcinoma (1 paper, 2021). A carcinoma that arises from epithelial cells of the prostate gland. "TAPBPL protein was expressed in liver, lung, and prostate cancer tissues at medium to high levels." (PMID 33938620, 2021). "Therefore, the expression of TAPBPL in liver, lung, and prostate cancer tissues was higher than that observed on matching normal tissues." (PMID 33938620, 2021).
cancer (9 papers, 2020 to 2026). A tumor composed of atypical neoplastic, often pleomorphic cells that invade other tissues. "The TAPBPL protein expression levels on the cancer cells were also consistent with the TAPBPL mRNA expression levels in these cells (Fig EV1F)." (PMID 33938620, 2021). "We also examined TAPBPL protein expression on cancer cell lines by flow cytometry." (PMID 33938620, 2021). "TAPBPL protein was largely located on the plasma membrane and cytoplasm of the cancer cells." (PMID 33938620, 2021). "Our results and those from others suggest that, like PD‐L1 and other T cell inhibitory molecules, TAPBPL may be involved in immune evasion of cancer." (PMID 33938620, 2021). "Similarly, using RNA-seq data, we found that a lower expression of APM-related genes, including B2M, CIITA, ERAP2, TAP2 and TAPBPL, was also associated with a shorter PFS, reflecting the increasing interest in APM biomarkers for clinical outcome and immune escape in cancer." (PMID 37799721, 2023). "The expression of FBP1 and TAPBPL was significantly high in BC tissues, and moderate expression of GPRC5C was found both in breast normal tissue and cancer tissue." (PMID 36358906, 2022).
tumor (7 papers, 2014 to 2025). "TAPBPL protein is expressed on resting and activated T cells, B cells, monocytes, and dendritic cells (DCs), as well as on some tumor tissues." (PMID 33938620, 2021). "Together, our results suggest that the anti‐TAPBPL mAb can inhibit tumor growth in vivo, which is related to neutralizing the inhibitory activity of TAPBPL on T cells in the tumor and spleen." (PMID 33938620, 2021). "We then assessed the expression of TAPBPL protein in human normal and tumor tissues by immunohistochemistry." (PMID 33938620, 2021). "A significant increase of TAPBPL expression level was observed in tumor samples when compared to the organ-specific control samples (p<0.001)." (PMID 25133526, 2014). "In contrast, anti‐TAPBPL antibody enhances antitumor immunity and inhibits tumor growth in vivo." (PMID 33938620, 2021). "Since TAPBPL is highly expressed in tumor tissues and TAPBPL‐Ig inhibits T‐cell functions, we hypothesized that anti‐TAPBPL antibody could block the inhibitory effect of TAPBPL, thereby enhancing antitumor immunity and inhibiting tumor growth in vivo." (PMID 33938620, 2021). "Furthermore, an anti‐TAPBPL monoclonal antibody neutralizes the inhibitory activity of hTAPBPL‐Ig on T cells, enhances antitumor immunity, and inhibits tumor growth in animal models." (PMID 33938620, 2021). "The expression of TAPBPL, SERPINB9, RCAN1, TMBIM4, JUNB, IL4R, and LY75 is significantly up-regulated in tumor samples with their high expression associated with a poor outcome; the expression of MGST3 is down-regulated in tumor samples with its low expression associated with poor prognosis." (PMID 25133526, 2014). "In the SWI/SNF-mutant cohort, a seven-gene signature comprising CRIM1 (angiogenesis), VEGFC (lymphangiogenesis), BMP7 (tumor microenvironment regulation), NR1D2 (immune modulation), BMPR1B (tumor proliferation), CR2 (B-cell activation), and TAPBPL (antigen presentation) was ultimately retained." (PMID 41438758, 2025).
TAPBPL also shares sentences with these, for which no sentence is quoted: colon cancer (1 paper); glioblastoma (1); infection (1); Lewis lung carcinoma (1); metabolic disorders (1); neuroblastoma (1); renal carcinoma (1); viral infection (1).